EGFR (epidermal growth factor receptor)
Diseases named in the same sentence as EGFR in open-access papers (continued):
Sharing a sentence is not in itself a finding about the gene and the disease.
lung cancer (continued). "The overexpression and activation of the epidermal growth factor receptor (EGFR), a transmembrane receptor tyrosine kinase that belongs to the ERBB family, facilitates tumor survival, proliferation, and cancer stemness in lung cancer." (PMID 31619200, 2019). "The genes tested were TBP as a housekeeping gene, EGFR, ERCC1 and RRM1 as genes with potential predictive roles for lung cancer therapy, and HIF1 as a gene regulated by hypoxia, at least partially on RNA level." (PMID 30947297, 2019). "Another important oncogene in lung cancer is the KRAS (Kirsten rat sarcoma viral oncogene homolog), which codifies an EGFR downstream GTPase20." (PMID 30824880, 2019). "In lung cancer studies, SMO amplifications and subsequent activation of the hedgehog pathway confer resistance to anti-EGFR drugs." (PMID 31565188, 2019). "It was initially found that ibrutinib exhibited potent antitumor effect against non‐small cell lung cancer (NSCLC) cells, but only those with EGFR‐mutant (L858R or 19Del)." (PMID 30663221, 2019). "Lung cancer cells harboring EGFR exon 19 deletion and DDX3X cDNA have been observed to have reduced EGFR-tyrosine kinase inhibitor (TKI) sensitivity and cancer stem cell phenotypes, suggesting a role for DDX3X in drug resistance acquisition." (PMID 31906196, 2019). "The DEGs centrally had direct interaction with EGFR, ERBB2, ERBB4, MET and TUBB, which suggested that the divergence between the primary CRC and the metastases of CRC was related to lung cancer." (PMID 30642283, 2019). "Furthermore, a sensitivity of 61% has been reported using MassARRAY to detect EGFR mutations in plasma ctDNA from lung cancer patients, while the SABER/MassARRAY method has been successfully used to detect the T790M EGFR mutation in EGFR-TKI refractory lung cancer patients." (PMID 31185703, 2019). "In our study, we have also performed head-to-head comparison of EGFR, ERBB2, and MET gene amplifications between tissue WES and ctDNA in 48 lung cancer patients." (PMID 31739500, 2019). "Treatment of lung cancer cells with a combination of MET siRNA and EGFR siRNA enhanced the growth inhibiting effect of EGFR siRNA alone." (PMID 31557260, 2019). "In the context of lung cancer, it will be of interest to assess the driver role of ADAM17 in other lung cancer subtypes (e.g., KRAS wild-type LAC, EGFR mutant LAC, squamous cell carcinoma)." (PMID 31438559, 2019). "Inhibition of LC3A expression using siRNA also decreased LC3B-II levels and cell proliferation, whereas a 5-azadC treatment restored LC3A expression in lung cancer PC9 cells and decreased their response to EGFR-TKI." (PMID 31861179, 2019). "Therefore, it appears that unlike, for example, lung cancer where there is a correlation between specific EGFR mutations and clinical responsiveness to EGFR tyrosine kinase inhibitors, in many cases response to rapalogs is not so easy to define based on genotype." (PMID 35582282, 2019). "Among the 28 cases of EGFR mutation positive and 20 cases of EGFR mutation negative previously tested on paraffin-embedded tissue by clinic test, 20 cases with EGFR mutation positive and 20 cases with negative were detected by matched fixation liquid of lung cancer biopsy, respectively." (PMID 31315782, 2019). "The recent identification of driver oncogenes, such as EGFR, ALK, ROS1, and BRAF has already been successfully translated into clinical practice for individuals with lung cancer." (PMID 31142054, 2019). "Compared to other EGFR inhibitors, AZD9291 has shown a good ability to inhibit tumor cell growth in a mouse model with brain metastases of lung cancer." (PMID 31122294, 2019). "Therefore, targeting RIC8A might be promising to prevent EGFR TKI resistance in lung cancer." (PMID 31741433, 2019). "HER3 mediates drug resistance against epidermal growth factor receptor (EGFR)-tyrosine kinase inhibitors (TKIs), resulting in tumor relapse in lung cancers." (PMID 31619200, 2019).
lung cancer (continued). "IGFBP3 up-regulation in lung cancer cells leads to increased MET expression via Smad2/3 activation and results in EGFR- and Met-TKI dual resistance." (PMID 30609749, 2019). "Therefore, despite the lower response of PD-1/PD-L1 therapy in EGFR mutant compared with EGFR wild-type patients, higher PD-L1 expression still indicates a better response to anti-PD-1/PD-L1 inhibitors in EGFR mutant advanced lung cancer patients who acquired EGFR-TKI resistance." (PMID 31747941, 2019). "The resulting network includes 43 TKs and 415 inferred, LUAD-specific substrates, which were validated at >60% accuracy by SILAC assays, including “novel’ substrates of the EGFR and c-MET TKs, which play a critical oncogenic role in lung cancer." (PMID 30615629, 2019). "In EGFR-mutant and ALK-rearranged lung cancers, early data on the decreased activity (compared with unselected cancers) of immunotherapy resulted in the exclusion of patients with these tumors in registration-enabling studies." (PMID 31192313, 2019). "The present study revealed the role of the transcriptional repression of miRNAs, such as miR-145-5p, by the STAT3-G9a axis in EGFR-positive lung cancers, which exacerbated HER3 expression and led to EGFR-TKI resistance." (PMID 31619200, 2019). "Previous findings indicated that EGFR binds to and phosphorylates SCD1 at Y55 for maintaining the stability of SCD1 protein, increasing the MUFA levels to promote lung cancer growth." (PMID 31019378, 2019). "As EGFR-mutated lung cancer favours female, never-smoker, adenocarcinoma and Asians, it may be argued that there may be some underlying genetic modifiers responsible for the pathogenesis of EGFR mutation." (PMID 31703574, 2019). "To elucidate the mechanisms of pemetrexed resistance in lung cancer, we established pemetrexed-resistant sublines in PC9 (mutant EGFR) and H1993 (wild-type EGFR) lung adenocarcinoma cell lines (PC9-MTA, H1993-MTA)." (PMID 30838090, 2019). "In EGFR-mutant lung cancer, BIM has a role in inducing cellular apoptosis after EGFR TKIs treatment." (PMID 31870097, 2019). "It was also proved that in H460 lung cancer cells, the suppression of Stearoyl-CoA Desaturase (SCD) activity, impairs the ligand-induced phosphorylation of EGFR." (PMID 30876460, 2019). "Especially, the identified genes EGFR, CDKN2A, ERBB2, RB1, and CDK4 were significantly enriched for non‐small cell lung cancer, demonstrating that UniCovEx accurately identified the cancer‐related gene modules." (PMID 30828525, 2019). "Gefitinib has been evaluated in the treatment of patients with lung cancer and other tumors and is able to reduce the onset of HCC tumors on cirrhosis via inhibiting the EGFR pathway." (PMID 31635301, 2019). "The efficacy of killing lung cancer cells and apoptosis induction by the LHRH-NLC-TAX multifunctional complex system was compared with a traditional clinically used EGFR-TK inhibitor - gefitinib." (PMID 31754402, 2019). "For example, EGFR activation in response to EGF binding mediates IL-6 production in ovarian and lung cancer cells." (PMID 31470515, 2019). "Lung cancer organoids respond to drugs based on their genomic alterations: a BRCA2-mutant organoid to olaparib, an EGFR-mutant organoid to erlotinib, and an EGFR-mutant/MET-amplified organoid to crizotinib." (PMID 31488816, 2019). "EGFR stabilizes SCD1 through Y55 phosphorylation, thereby up-regulating MUFA synthesis to promote lung cancer growth." (PMID 31019378, 2019). "In particular, an induction of EMT was reported to decrease the therapeutic efficacy of the first generation EGFR-TKI and cytotoxic anti-cancer drugs in lung cancer patients." (PMID 30800222, 2019). "In parallel, we adapted two EGFR‐mutant and TKI‐sensitive lung cancer cell lines, PC‐9 and HCC827, to IL‐6 and cultured for 72 hours to simulate the in vivo microenvironment." (PMID 31507089, 2019).
lung cancer (continued). "In lung cancer, SPRY4 is a promising target to interdict the progress of NSCLC therapy engaged in the progression of EGFR-mediated ovarian cancer and enhances melanoma cell motility and treatment of gastrointestinal tumors." (PMID 30390072, 2019). "The role of AQP3 in EGFR-dependent cell signaling and cancer progression was investigated in human squamous cell carcinoma and human lung cancer cell lines, both expressing high concentrations of AQP3 and EGFR." (PMID 30893772, 2019). "In addition, a previous study indicated that AR is significantly over-expressed in non-responders, but undetectable in responders, which may biologically affect drug sensitivity and lead to the resistance of non–small cell lung cancer (NSCLC) cells to EGFR tyrosine kinase inhibitors in vitro." (PMID 31370819, 2019). "In a recent study researcher found EGFR stabilizes SCD1 and up-regulating MUFA synthesis to promote lung cancer growth." (PMID 30876460, 2019). "The most common type of lung cancer is non-small cell lung carcinoma (NSCLC), and it is characterized by EGFR overexpression." (PMID 31109009, 2019). "To elucidate the relationship between EHD1 expression and EGFR-TKI resistance, we retrospectively evaluated specimens from a total of 24 lung cancer patients who had received EGFR-TKIs (erlotinib or gefitinib)." (PMID 29549343, 2018). "To further examine the role of MET in EGFR-TKI-naïve cancer cells, we developed another resistant cell line from EGFR-TKI-naïve lung cancer cells, HCC827, which harbor the EGFR exon 19del." (PMID 29386539, 2018). "In combination with EGFR inhibitors, AZ1366 synergistically suppressed proliferation of multiple lung cancer lines." (PMID 29458371, 2018). "The epidermal growth factor receptor (EGFR) is a type-1 transmembrane receptor tyrosine kinase, which activates the downstream signaling cascades in many tumors, such as oral and lung cancers." (PMID 29872734, 2018). "EGFR, a member of the HER receptor tyrosine kinase family, is a known oncogenic protein in solid tumors, particularly in lung cancer." (PMID 29455656, 2018). "reduced xenograft tumor size in nude mice and Moreover, combined EGFR TKI and a YAP inhibitor, statin, prolonged survival among lung cancer patients analyzed by Taiwan National Health Insurance Research database." (PMID 29321482, 2018). "In the present study, we for the first time demonstrated that administration of elemene significantly enhanced cellular responses to the canonical EGFR-TKI gefitinib, inhibiting cellular proliferation and inducing progressive apoptosis in lung cancer cells." (PMID 30555330, 2018). "Since PHLDA2 is a downstream target of EGFR/ErbB2, we analyzed PHLDA2, p-Erk and p-AKT expression in multiple lung cancer cell lines and a tissue microarray prepared with 117 well annotated primary lung cancer samples." (PMID 29861842, 2018). "It is identified by Lin and colleagues that METTL3 boosts translation of certain mRNAs including epidermal growth factor receptor (EGFR) and the Hippo pathway effector TAZ, thus promoting growth, survival, and invasion of human lung cancer cells." (PMID 29587823, 2018). "In addition, EGFR contains other SNPs that were not investigated in the current study and might be associated with lung cancer among Jordanians." (PMID 30011810, 2018). "Between July 2013 and June 2017, 206 patients with pathologically confirmed lung cancer were screened with a next-generation sequencing (NGS) panel including HER2 and EGFR genes at Kindai University Hospital." (PMID 29765525, 2018). "In contrast to the situation in lung cancer, Cx43 is increased with the formation of GJIC in the resistant tumour cells and this increase is induced by epidermal growth factor receptor (EGFR) activated JNK-ERK1/2-AP-1 signalling." (PMID 29865195, 2018). "Sensitivities of 0.005–0.1% for EGFR-T790M (own unreported data,), 0,1% and 0,5% for ALK-C1156Y and ALK-G1269A in lung cancer and 0.025% for KRAS in CRC are reached." (PMID 29568401, 2018).
lung cancer (continued). "Osimertinib has evidenced significant anti-cancer efficacy in lung cancer patients who are positive for T790M; in particular, PFS after acquired resistance to afatinib was longer than with 1st generation EGFR-TKI." (PMID 30550608, 2018). "NEDD4 was co-immunoprecipitated with EGFR upon EGF stimulation in both A549 and H358 cells, suggesting that NEDD4 specifically interacts with activated EGFR in lung cancer cells." (PMID 29455656, 2018). "Epidermal growth factor receptor (EGFR) has been proved to be related with the pathogenesis and progression of multiple carcinoma types, including lung cancer, breast cancer, prostatic cancer and pancreatic cancer." (PMID 30393665, 2018). "Not only is the expression of slug regulated by EGFR signaling pathway but also it is induced by hepatocyte growth factor (HGF)/c-Met-mediated signaling pathway in murine colorectal and lung cancer cells." (PMID 29681982, 2018). "In our laboratory, we selected as the target receptor human epidermal growth factor receptor 2 (HER2) (20, 22, –, 27), a member of the epidermal growth factor receptor (EGFR) family of receptors, present in a subset of breast, ovary, stomach, and lung cancers." (PMID 29263257, 2018). "Furthermore, multivariate analysis showed that lung cancer patients whose blood IGFBP2 was higher had a poor survival outcome, with a hazard ratio of 8.22 (95%CI 1.78–37.92, P = 0.007) after adjustment for stage, histopathology, EGFR mutation, age, smoking and surgery." (PMID 29500455, 2018). "Icotinib and Endostar are primary research drugs in China, and studies have shown that they are as effective as the other first-generation drugs EGFR-TKI and bevacizumab in patients with lung cancer in China." (PMID 30257820, 2018). "Together, these results highlight the important role of MGL in regulation of EGFR/ERK and Akt signaling in lung cancer." (PMID 29348400, 2018). "In NSCLC, EGFR is upregulated and amphiregulin (AREG), an EGFR ligand, is packaged in exosomes derived from lung cancer cells." (PMID 29720982, 2018). "PC9 cells that were made resistant to erlotinib exhibited drug-resistant mitogen-activated protein kinase (MAPK) activity, which has also been described as a mechanism of acquired EGFR inhibitor resistance in both PC9 cells and in lung cancer patients." (PMID 29874589, 2018). "The Epidermal Growth Factor Receptor (EGFR) inhibitor Erlotinib also showed synergistic effect with Sorafenib and increased RKIP expression in lung cancers." (PMID 30181452, 2018). "In human lung cancer cells, METTL3 promotes the translation of specific genes, such as EGFR (epidermal growth factor receptor) and Hippo pathway effector, TAZ (tafazzin), through recruitment of eIF3 to the translation initiation complex." (PMID 29439529, 2018). "About 80% of advanced NSCLC patients benefit from the clinical application of EGFR TKI, which has led to the revolution in the lung cancer therapy." (PMID 29573196, 2018). "Other experimental candidates include scFv, affibody and minibody (ERBB2/HER2 and FGFR1), Protein–Fc (VEGFR1 and VEGFR2) and Intact IgG (EGFR, ERBB2, and VEGF) in breast and lung cancer studies." (PMID 29455673, 2018). "Inhibition of cell migration and invasion by propolin C was through the inhibition of EGF/EGFR-mediated signaling pathway, followed by EMT suppression in lung cancer." (PMID 29681982, 2018). "Several small molecule targeted agents have been developed against the EGFR and ALK tyrosine kinases, which have increased hope for patients with brain metastases of lung cancer." (PMID 29435193, 2018).
lung cancer (continued). "Controlling lung cancer cell migration and invasion via epithelial-to-mesenchymal transition (EMT) through the regulation of epidermal growth factor receptor (EGFR) signaling pathway has been demonstrated." (PMID 29681982, 2018). "However, how NEDD4 promotes the EGFR-dependent lung cancer cell migration is unknown." (PMID 29455656, 2018). "However, the relevance of differentially located EGFR proteins in lung cancer remains unclear." (PMID 29950164, 2018). "The discovery and development of therapeutics targeting epidermal growth factor receptor (EGFR), namely tyrosine kinase inhibitors (TKIs), in the past decade was an important clinical advance in non–small cell lung cancer (NSCLC) treatment." (PMID 30068310, 2018). "In the top 50 potential lung cancer-related miRNAs, miR-133a plays a tumor suppressor role in non-small cell lung cancer (NSCLC) by targeting IGF-1R, TGFBR1 and EGFR." (PMID 29498680, 2018). "Several in vitro studies have shown that acute exposure to cigarette smoke mediates development of lung cancer and resistance to TKIs in NSCLC in both wild type (WT) EGFR and TKI sensitive mutants." (PMID 29556515, 2018). "In lung cancer, amplification of MET is reported to be a mechanism of resistance to epidermal growth factor receptor-targeted tyrosine kinase inhibitors (EGFR-TKIs)." (PMID 29890660, 2018). "miR-193a can also act as a tumor suppressor by targeting ERBB4 (human EGFR 2, HER2) and play a role in inhibiting proliferation and invasion and accelerating the apoptosis of lung cancer cells." (PMID 29016617, 2017). "EGFR activation induces EMT, resulting in resistance to cetuximab or IR in HNSCCs and erlotinib resistance in lung cancers." (PMID 28423495, 2017). "Transferrin receptor, FRA, EGFR, integrins, and CD44 are common receptors that have been explored for targeted nanoparticle-based gene delivery in lung cancer." (PMID 28290155, 2017). "In this paper, we find that EGFR-mediated Y55 phosphorylation maintains SCD1 protein stability, thus increasing intracellular MUFA level to promote lung cancer growth." (PMID 28724430, 2017). "Epidermal growth factor receptor (EGFR) and anaplastic lymphoma kinase (ALK) are the two common biological targets for lung cancer drug development." (PMID 28615068, 2017). "For EGFR and KRAS involved in lung cancers, striking differences in molecular alterations of these genes have been found in never and ever smokers." (PMID 28430611, 2017). "More than 80% of lung cancer is non-small cell lung cancer (NSCLC), and the epidermal growth factor receptor (EGFR)-mediated signaling pathway is closely related to the occurrence and development of NSCLC." (PMID 29277186, 2017). "In our results, we demonstrated abolishing both EGFR and AKT signaling by VJ treatment to suppress the growth of lung cancer cells." (PMID 29234489, 2017). "GEF is a selective EGFR-TKI and was the first approved for clinical use as an orally administered drug for patients with lung cancer." (PMID 28961023, 2017). "Recent advances in cancer therapeutics have shown that identifying molecular targets for lung cancer treatment such as vascular endothelial growth factor (VEGF) and epidermal growth factor receptor (EGFR) is important to improve patient survival." (PMID 29121075, 2017). "ML-18 inhibited the ability of BA1 to increase cytosolic calcium and tyrosine phosphorylation of EGFR and ERK in lung cancer cells." (PMID 29262666, 2017). "And repressed GPRC5A correlates with activated EGFR and STAT3 signaling in lung cancer, which explains dysregulated STAT3 induced by aberrantly activated EGFR in lung cancer." (PMID 28270740, 2017). "Recently, epidermal growth factor receptor (EGFR) and anaplastic lymphoma kinase (ALK) have been determined to be the most effective molecules for targeted therapy in lung cancer." (PMID 28272300, 2017). "High levels of EGFR expression can activate the downstream PI3K/AKT and MAPK/ERK to promote the proliferation and metastasis of lung cancers." (PMID 29152147, 2017).